POLR1E (RNA polymerase I subunit E)
Description:
Component of RNA polymerase I (Pol I), a DNA-dependent RNA polymerase which synthesizes ribosomal RNA precursors using the four ribonucleoside triphosphates as substrates. Appears to be involved in the formation of the initiation complex at the promoter by mediating the interaction between Pol I and UBTF/UBF.
Synonyms: PAF53; PRAF1; FLJ13390; FLJ13970; RPA49; A49
Tractability: Small molecule: a structure with a bound ligand is known. PROTAC: ubiquitination databases record sites on it; its protein half-life has been measured.
Gene: Protein-coding gene on chromosome 9 (37,481,695 to 37,503,701, forward strand). Ensembl gene ENSG00000137054.
Subcellular location: Nucleus, nucleolus
Subcellular location (Human Protein Atlas): Nucleoli fibrillar center; Nucleoplasm
Pathways (Reactome):
Gene expression (Transcription): B-WICH complex positively regulates rRNA expression; NoRC negatively regulates rRNA expression; RNA Polymerase I Promoter Escape; RNA Polymerase I Transcription Initiation; RNA Polymerase I Transcription Termination
Gene Ontology:
Molecular function: protein binding; DNA binding; RNA polymerase I general transcription initiation factor binding
Biological process: nucleolar large rRNA transcription by RNA polymerase I; transcription elongation by RNA polymerase I; transcription initiation at RNA polymerase I promoter; RNA polymerase I preinitiation complex assembly; termination of RNA polymerase I transcription; DNA-templated transcription
Cellular component: fibrillar center; nucleoplasm; RNA polymerase I complex; nucleolus; nucleus
Genetic constraint (gnomAD): Loss-of-function variants: 37 observed, 43.33 expected, observed/expected ratio (o/e) 0.85, 90% interval 0.66 to 1.12. The upper end of that interval is the gene's LOEUF score, 1.12, which puts it in group 4 of 6, group 1 being the genes least tolerant of losing a copy. Missense variants: 392 observed, 477.32 expected, observed/expected ratio (o/e) 0.82, 90% interval 0.75 to 0.89. Synonymous variants: 152 observed, 179.98 expected, observed/expected ratio (o/e) 0.84, 90% interval 0.74 to 0.97.
Homologues: Orthologues: macaque POLR1E (98% identical), chimpanzee POLR1E (95% identical), pig POLR1E (88% identical), guinea pig POLR1E (84% identical), rabbit POLR1E (84% identical), rat Polr1e (78% identical), mouse Polr1e (77% identical), dog POLR1E (70% identical), tropical clawed frog polr1e (51% identical), zebrafish polr1e (40% identical), Caenorhabditis elegans rpoa-49 (19% identical), Drosophila melanogaster Polr1E (17% identical).
Diseases named in the same sentence as POLR1E in open-access papers:
POLR1E is named in the same sentence as 9 diseases in open-access papers, as found by Europe PMC text mining. Sharing a sentence is not in itself a finding about the gene and the disease. The quoted sentences say what the papers report.
breast carcinoma (1 paper, 2022). "Additionally, we observed downregulation of genes such as POLR1A, POLR1D, POLR1E, TAF1B, LAMP1, and CDKN1A in response to AQ treatment demonstrating the role of AQ in regulating RNA polymerase subunits and effect on overall gene transcription in breast cancer." (PMID 36232751, 2022).
colorectal cancer (1 paper, 2024). A primary or metastatic malignant neoplasm that affects the colon or rectum. "Indeed, POLR1E is part of enriched signaling pathways in colorectal cancer while these member of the STAT family are contributing to promotion of colorectal tumorigenesis, silencing them inhibits cell proliferation and invasion of colorectal cancer cells, and considered as targets for therapy." (PMID 38632500, 2024).
cancer (2 papers, 2020 to 2023). A tumor composed of atypical neoplastic, often pleomorphic cells that invade other tissues. "Importantly, basal cancers express high mRNA levels of genes encoding regulators of ribosome biogenesis such as BYSL, RRS1, RIOK1, POLR1C, and POLR1E (group C)." (PMID 32054925, 2020).
tumor (1 paper, 2022). "We tested 24 tumor samples for BRCA1 and BRCA2 mRNA levels, normalized to the reference genes GUSB, POLR1E, and NUBP1." (PMID 35203410, 2022).
POLR1E also shares sentences with these, for which no sentence is quoted: infection (2 papers); viral infection (2); AIDS (1); bladder cancer (1); smallpox (1).